LINC01290 (long independently transcribed non-coding RNA 1290)
Gene: Long non-coding RNA gene on chromosome 16 (10,514,842 to 10,528,202, reverse strand). Ensembl gene ENSG00000260468.
Diseases named in the same sentence as LINC01290 in open-access papers:
LINC01290 is named in the same sentence as 1 disease in open-access papers, as found by Europe PMC text mining. Sharing a sentence is not in itself a finding about the gene and the disease. The quoted sentences say what the papers report.
cancer (1 paper, 2022). A tumor composed of atypical neoplastic, often pleomorphic cells that invade other tissues. "Dysregulation of the lncRNAs MBNL1-AS1, CCDC18-AS1, LINC01290, MIR29B2CHG, and PSMB8-AS1 has been observed in many cancers." (PMID 36619896, 2022).